VCAM1 (vascular cell adhesion molecule 1)
Description:
Cell adhesion glycoprotein predominantly expressed on the surface of endothelial cells that plays an important role in immune surveillance and inflammation. Acts as a major regulator of leukocyte adhesion to the endothelium through interaction with different types of integrins. During inflammatory responses, binds ligands on the surface of activated endothelial cells to initiate the activation of calcium channels and the plasma membrane-associated small GTPase RAC1 leading to leukocyte transendothelial migration. Also serves as a quality-control checkpoint for entry into bone marrow by providing a 'don't-eat-me' stamping in the context of major histocompatibility complex (MHC) class-I presentation.
Synonyms: CD106; INCAM-100
Tractability: Small molecule: it has a binding pocket of medium quality; it belongs to a druggable protein family. Antibody: UniProt places it where antibodies can reach, with high confidence; its Gene Ontology location is reachable by antibodies, with high confidence; UniProt predicts a signal peptide or a membrane-spanning region. PROTAC: UniProt records ubiquitination sites on it; its protein half-life has been measured; a small molecule that binds it is known.
Target class: Adhesion
Gene: Protein-coding gene on chromosome 1 (100,719,684 to 100,739,045, forward strand). Ensembl gene ENSG00000162692.
Subcellular location: Cell membrane (Vascular cell adhesion protein 1); Secreted (Soluble Vascular Cell Adhesion Molecule-1)
Subcellular location (Human Protein Atlas): Cell Junctions; Predicted to be secreted
Pathways (Reactome):
Immune System: Immunoregulatory interactions between a Lymphoid and a non-Lymphoid cell; Interferon gamma signaling; Interleukin-4 and Interleukin-13 signaling
Extracellular matrix organization: Integrin cell surface interactions
Gene Ontology:
Molecular function: cell adhesion mediator activity; cell adhesion molecule binding; integrin binding; primary methylamine oxidase activity
Biological process: amine metabolic process; cell adhesion; cell-cell adhesion mediated by integrin; cell-matrix adhesion; cellular response to amyloid-beta; heterophilic cell-cell adhesion; heterotypic cell-cell adhesion; inflammatory response; leukocyte cell-cell adhesion; leukocyte tethering or rolling; membrane to membrane docking; positive regulation of T cell proliferation; B cell differentiation; cardiac neuron differentiation; cell adhesion mediated by integrin; cell-cell adhesion; cellular response to tumor necrosis factor; chronic inflammatory response; innervation; response to ethanol; response to hypoxia; response to ionizing radiation; response to lipopolysaccharide; response to nicotine; response to nutrient; and 1 more
Cellular component: alpha9-beta1 integrin-vascular cell adhesion molecule-1 complex; apical part of cell; cell surface; early endosome; endoplasmic reticulum; external side of plasma membrane; extracellular exosome; extracellular region; filopodium; Golgi apparatus; microvillus; podosome; plasma membrane; membrane; sarcolemma
Genetic constraint (gnomAD): Loss-of-function variants: 41 observed, 63.53 expected, observed/expected ratio (o/e) 0.65, 90% interval 0.5 to 0.84. The upper end of that interval is the gene's LOEUF score, 0.84, which puts it in group 3 of 6, group 1 being the genes least tolerant of losing a copy. Missense variants: 792 observed, 911.82 expected, observed/expected ratio (o/e) 0.87, 90% interval 0.82 to 0.92. Synonymous variants: 338 observed, 333.1 expected, observed/expected ratio (o/e) 1.01, 90% interval 0.93 to 1.11.
Homologues: Orthologues: macaque VCAM1 (94% identical), chimpanzee VCAM1 (87% identical), rabbit VCAM1 (87% identical), dog VCAM1 (81% identical), guinea pig VCAM1 (78% identical), rat Vcam1 (77% identical), mouse Vcam1 (76% identical), pig VCAM1 (55% identical), zebrafish vcam1b (25% identical), Caenorhabditis elegans igdb-2 (17% identical), Caenorhabditis elegans igdb-1 (13% identical). Paralogues in human: CNTN6 (17% identical), HMCN2 (17% identical), ROBO2 (17% identical), SDK1 (17% identical), CHL1 (17% identical), NRCAM (17% identical), ROBO1 (17% identical), SDK2 (17% identical), DCC (17% identical), IGSF10 (17% identical), CNTN3 (16% identical), CNTN4 (16% identical), and 24 more.
Diseases named in the same sentence as VCAM1 in open-access papers:
VCAM1 is named in the same sentence as 608 diseases in open-access papers, as found by Europe PMC text mining. Sharing a sentence is not in itself a finding about the gene and the disease. The quoted sentences say what the papers report.
atherosclerosis (781 papers, 2005 to 2026). A disease characterized by the build-up of fatty material and calcium deposition in the arterial wall resulting in partial or complete occlusion of the arterial lumen. "Vcam1 encodes the important cell adhesion molecule VCAM1, which promotes the adhesion of immune cells to the vessel wall and is one of the key markers of atherosclerosis." (PMID 41450877, 2025). "The findings presented emphasize the potential of VCAM-1 and E-selectin as important biomarkers for cardiovascular risk in psoriasis, shedding light on their implications in atherosclerosis, vasculitis, cancer, and other inflammatory conditions." (PMID 39859506, 2025). "The presence of thymol (3 and 6 mg/kg/day) also decreased the expression levels of atherosclerosis-associated indicators, namely, vascular cell adhesion molecule-1 (VCAM-1), MCP-1, and MMP-9, shifting the effect of high-fat and high-cholesterol diet." (PMID 40509336, 2025). "Induction of VCAM1, a leukocyte adhesion receptor implicated in atherosclerosis, was strongly suppressed by Tz." (PMID 39703699, 2024). "MB-coated VCAM-1 specific scFv have been investigated for imaging vascular inflammatory responses associated with atherosclerosis and abdominal aortic aneurysm (AAA)." (PMID 39735545, 2024). "Apart from VCAM-1, another biomarker of atherosclerosis to be targeted by various diagnostic scFv is electronegative LDL (−), a physiologically modified LDL that exerts atherogenic effects in macrophages by promoting differentiation and inflammation." (PMID 39735545, 2024). "Vascular cell adhesion protein 1 (Vcam1) is a marker of inflammation and is associated with atherosclerosis susceptibility." (PMID 39337408, 2024). "An association between endothelial dysfunction leading to inflammation and atherosclerosis is given by atherosclerosis-associated endothelial–leukocyte adhesion molecule (VCAM-1)." (PMID 38474211, 2024). "VCAM-1, encoding vascular cell adhesion molecule-1, is a well-established NF-κB target gene and the protein product is associated with atherosclerosis." (PMID 38335214, 2024). "To validate sensitivity towards the known genes implicated in phenotypic switching of SMCs in atherosclerosis, we confirmed that markers of synthetic SMCs (Fn1, Col1a1, Col3a1, Col1a2, Eln, and Vcam1) were elevated in SMCTRAP-AS compared with SMCTRAP." (PMID 38289873, 2024). "CEBPD and RUNX1 were identified as the key regulators for both atherosclerosis-associated cell states despite the higher expression of Cebpd in Vcam1+ SMCs and Runx1 in Col2a1+ SMCs." (PMID 37060905, 2023). "Using single-cell RNA sequencing, researchers identified 12 atherosclerosis-associated cell states and found that Vcam1+ smooth muscle cell state contributed the most to the genetic heritability of coronary artery disease." (PMID 37060905, 2023). "It has been reported that accumulation of ICAM-1, TNF-RII, VCAM-1, and D-dimer in the vessel wall is a hallmark of atherosclerosis and acute coronary syndrome and is mediated by the interaction between adhesion molecules on endothelial and circulating cells." (PMID 37828979, 2023). "VCAM-1 was significantly higher in boys than girls, which showed that boys had a higher risk of atherosclerosis." (PMID 37822716, 2023). "P2Y1 receptor knockout in apolipoprotein E-deficient mice decreases macrophage infiltration and VCAM-1 levels, indicating that atherosclerosis is related to the P2Y1 receptors on ECs." (PMID 34981330, 2023). "P2Y2 receptor causes vascular inflammation by increasing VCAM-1 expression in ECs, which eventually causes atherosclerosis." (PMID 34981330, 2023). "Monocyte-endothelial adhesion mediated by ICAM-1 and VCAM-1 is an important early step in atherosclerosis, which is a major cause of cardiovascular disease." (PMID 37228610, 2023).
atherosclerosis (continued). "And deficiency of CD11c on APOE double deficiency mice reduces the firm attachment of monocytes to VCAM1, P Selectin which are proinflamatory cytokine for the development of atherosclerosis." (PMID 35241081, 2022). "In the KEGG signaling pathway analysis of DEGs, we found that RES was associated with fluid shear stress and atherosclerosis, including VCAM1, ICAM1, PECAM1, and other adhesion molecules closely related to atherosclerosis." (PMID 36364780, 2022). "Vascular cell adhesion molecule 1 (VCAM-1), which mediates leukocyte–endothelial cell adhesion, has been proven to be associated with atherosclerosis." (PMID 35215505, 2022). "The EC1 subtype highly expressed Vcam1 and Scarb2 genes in the aortic arch, which were reported to be associated with atherosclerosis." (PMID 35473929, 2022). "This study showed that the EC1 subtype highly expressed Vcam1 and Scarb2 genes in the aortic arch, which are reported to be associated with atherosclerosis." (PMID 35473929, 2022). "VCAM-1 is also implicated as a key mediator in atherosclerosis, where its expression was abundantly detected at atherosclerotic lesion sites." (PMID 35251216, 2022). "Given its role as a foothold for leukocyte recruitment, VCAM1 has been implicated in the pathogenesis of numerous inflammatory diseases including rheumatoid arthritis, asthma and atherosclerosis." (PMID 36091042, 2022). "Abnormal expression of VCAM-1 has been associated with various CVDs, including hypertension, cardiac remodeling, ischemic disease, atherosclerosis, and AF." (PMID 35222039, 2022). "It is also useful for the detection of activated endothelium at the risk of developing plaques, because VCAM-1 is a major participant during the initiation of atherosclerosis." (PMID 33464410, 2021). "Neutralization of IL-17A in SOCS3-deficient mice enhanced atherosclerosis development associated with T cell accumulation in the aorta and elevated vascular cell adhesion molecule 1 (VCAM-1) expression." (PMID 33562334, 2021). "Higher levels of VCAM-1/ICAM-1 are associated with atherosclerosis which take part in the disease progression as ICAM-1 help in transmigration of the immune cells in the sub-endothelial space." (PMID 33925294, 2021). "Intercellular adhesion molecule-1 (ICAM-1) and vascular cell adhesion molecule-1 (VCAM-1) are considered important risk factors involved in the development of atherosclerosis." (PMID 34388961, 2021). "Soluble VCAM1 has been reported to be a biomarker of endothelial dysfunction associated with both hypertension and atherosclerosis." (PMID 33971895, 2021). "In summary, VCAM-1 imaging enables us to detect atherosclerotic plaques, stratify the risk and evaluate a new therapy in atherosclerosis in animal studies." (PMID 33138124, 2020). "Atherosclerosis is associated with increased endothelial cell (EC) expression of adhesion molecules, especially VCAM-1." (PMID 33138124, 2020). "An increase in the contentof ICAM-1, VCAM-1, and E-selectin on the surface ofendothelial cells and in plasma is associated with the risk ofcoronary heart disease, atherosclerosis(Galkina, Ley, 2007), and pulmonary hypertension." (PMID 33659786, 2020). "Previous flow studies have shown that disturbed blood flow patterns upregulate a number of genes implicated in atherosclerosis such as vascular cell adhesion molecule 1 (VCAM1), E‐selectin, and monocyte chemoattractant protein 1 (MCP1)." (PMID 33080110, 2020). "Endothelial markers, ICAM-1 and VCAM-1, are implicated in atherosclerosis and associated with cardiovascular risk." (PMID 31370809, 2019). "In recent years, studies have shown that NF-ΚB and VCAM-1 are closely related to the formation of atherosclerosis, causing deviant cell proliferation and inflammatory response, thereby affecting the stability of plaques." (PMID 31888640, 2019). "In contrast, IL-9 was functionally linked to aggravated atherosclerosis in Apoe−/− mice by the induction of vascular cell adhesion molecule 1 expression." (PMID 31641089, 2019).
atherosclerosis (continued). "The molecule that is encoded by the VCAM-1 gene has long been postulated to play a more critical role in the development of atherosclerosis." (PMID 30524759, 2018). "In contrast to eNOS, AT1R, when activated by angiotensin II and atherosclerosis-inducing factors such as TNFα and VCAM1 causes hypertension through vasoconstriction." (PMID 30643517, 2018). "Analysis of atherosclerotic lesions of P2Y6 KO mice revealed fewer macrophages, diminished RNA expression of IL-6 and VCAM-1, suggesting that deficiency in this ATP receptor limits atherosclerosis and plaque inflammation." (PMID 29375564, 2017). "Here we found that IL-27R signaling during the early phase of atherosclerosis development is implicated into the regulation of the adhesion molecules VCAM-1, P-selectin, E-selectin and PECAM-1 expression by vascular endothelial cells." (PMID 28536468, 2017). "In the pathology of atherosclerosis, NF-κB activation is believed to underlie the regulated expression of VCAM-1." (PMID 28153917, 2017). "To determine the effect of P. gingivalis infection on expression of atherosclerosis-associated proteins, we measured expression of three adhesion molecules (E-selectin, VCAM1, and ICAM-1) in HUVECs at the transcriptional level using qRT-PCR." (PMID 27826542, 2016). "IL-1α is associated with CVD and can contribute to atherosclerosis through the expression of cell-adhesion molecules (vascular cell-adhesion molecule-1 and intracellular adhesion molecule-1)." (PMID 25648164, 2015). "In conclusion, this study is the first to demonstrate in vitro a regulatory mechanism involved in the production of MCP-1 and VCAM-1 in three cellular models that mimic the endothelial dysfunction caused by AGEs in the early events of atherosclerosis." (PMID 26008233, 2015). "A number of studies have used animal models to investigate the association between VCAM-1 and the pathogenesis of atherosclerosis." (PMID 26622332, 2015). "Certainly, we cannot prove a causal role of VCAM-1 for atherosclerosis in this particular population." (PMID 26066045, 2015). "This study demonstrates, in vitro, the regulatory mechanisms involved in MCP-1 production in three cellular models and VCAM-1 production in HUVECs, and thus mimics the endothelial dysfunction caused by AGEs in early atherosclerosis." (PMID 26008233, 2015). "In conclusion, aortic VCAM-1 expression is associated with the severity of atherosclerosis and cardiovascular risk factors, indicating that VCAM-1 plays a role in the pathogenesis of atherosclerosis." (PMID 26622332, 2015). "VCAM-1 was expressed in the areas that are predisposed to the development of atherosclerosis in animal models." (PMID 26610475, 2015). "Studies have shown that abnormal lipid metabolism is closely associated with the occurrence and development of atherosclerosis; therefore, the blood lipid levels and their possible association with VCAM-1 expression were examined in the present study." (PMID 26622332, 2015). "Increased levels of ICAM-1 and VCAM-1 have been associated with the early events of atherosclerosis." (PMID 26622474, 2015). "Systemic levels of ICAM-1 and VCAM-1 are associated with intimal-medial thickness and the degree of atherosclerosis in hypertensive type-2 diabetic patients." (PMID 26622474, 2015). "The major risk factors of atherosclerosis significantly improved the level of ICAM-1 or VCAM-1 expression in vascular intima." (PMID 26398523, 2015). "Higher levels of soluble VCAM-1 have been documented in subjects with type 2 diabetes, metabolic syndrome, and atherosclerosis, and have been associated with increased CVD mortality." (PMID 23886346, 2013). "Vascular cell adhesion molecule-1 (VCAM-1) is a cytokine-inducible member of the immunoglobulin gene superfamily that is expressed by endothelial cells in regions predisposed to atherosclerosis and at the borders of atherosclerotic plaques." (PMID 22474431, 2012).